PDCD6 (programmed cell death 6)
Diseases named in the same sentence as PDCD6 in open-access papers (continued):
Sharing a sentence is not in itself a finding about the gene and the disease.
tumor (continued). "One of the new candidate gene on this locus is PDCD6 which has been shown to contribute towards tumor development and expansion." (PMID 21386901, 2011). "Inhibition of PDCD6 expression can reduce the rate of tumor metastasis." (PMID 35503998, 2022). "Immunohistochemical examination of the tumor xenografts revealed that the phosphorylation of c-Raf/MEK/ERK was markedly suppressed in PDCD6-KD HCT116 cells xenografts, whereas c-Raf/MEK/ERK phosphorylation was markedly enhanced in the PDCD6-OE compared with the vector control cell xenografts." (PMID 32746883, 2020). "Furthermore, we explored the correlation between PDCD6 expression and the MAPK signal pathway downstream associated genes in tumor tissues." (PMID 32746883, 2020). "Overall, these data reveal that PDCD6 overexpression promotes tumor cell growth." (PMID 32746883, 2020). "Moreover, PDCD6 overexpression tends to positively correlate with the tumor stage in patients with CRC, indicating a potential correlation between PDCD6 and malignancies." (PMID 32746883, 2020). "Furthermore, immunofluorescence analysis also showed higher expression levels of PDCD6 in tumor tissues than in normal tissues of the same representative CRC samples." (PMID 32746883, 2020). "So, the opposite effect of PDCD6 might due to the opposite role of raf in different tumor types, in which the tissue-specific tumor microenvironment and the intensity of which signal activated are different." (PMID 32746883, 2020). "PDCD6 is aberrantly expressed in several neoplasias and is important for tumor cell viability." (PMID 29672642, 2018). "PDCD6 mRNA expression was significantly correlated with residual tumor size." (PMID 22369209, 2012). "Therefore, we speculated that tumor microenvironment or signal specificity lead to different roles of PDCD6 in tumors." (PMID 35503998, 2022). "Furthermore, PDCD6 increased cell proliferation in vitro and tumor growth in vivo." (PMID 32746883, 2020). "The qRT-PCR analysis was performed using PDCD6-KD and PDCD6-OE HCT15 cells to analyze the transcription levels of 9 important genes, which are known to take part in tumor progression." (PMID 32746883, 2020). "We proved that PDCD6 and c-RAF/MEK/ERK were positively correlated at the protein level by IHC in tumor tissues from xenografts and patients with CRC, which will further facilitate translational medicine research on PDCD6." (PMID 32746883, 2020). "PDCD6 has not been defined as an oncogene or tumor suppressor as it has opposing effects in different types of tumors." (PMID 35396512, 2022). "Similar results were found when categorical variable was analyzed, but significant difference of PDCD6 expression was showed between the patients with residual tumor and without residual tumor after surgery." (PMID 22369209, 2012). "Patients who had residual tumor after surgery had higher PDCD6 expression than patients who had no residual tumor, 0.31 versus 0.18, p = 0.261." (PMID 22369209, 2012). "Patients with residual tumor had significantly higher PDCD6 expression than patients who had no residual tumor (29.3% versus 16.7%, P = 0.050)." (PMID 22369209, 2012). "First, PDCD6 may promote disease progression or reduce the effect of adjuvant treatment by stimulating tumor cell migration or invasion, but these effects do not lead to the death of all cases." (PMID 22369209, 2012). "Patients with residual tumor had higher PDCD6 expression than patients with no residual tumor." (PMID 22369209, 2012).
infection (2 papers, 2020 to 2022). The state of being infected such as from the introduction of a foreign agent such as serum, vaccine, antigenic substance or organism. "During the WSSV infection, the level of miR-9875 was significantly decreased, leading to the accumulation of PDCD6, followed by the triggering of apoptosis and then attenuate WSSV replication." (PMID 32597292, 2020). "Similarly, PDCD6 was found to be enriched by GRA64 pulldown during neuron infection, confirming the LC-MS/MS findings." (PMID 35730903, 2022). "Clear enrichment of TSG101 and PDCD6 was observed in the human foreskin fibroblast infection eluates from 3×HA-GRA64 samples, but not in the untagged control eluates." (PMID 35730903, 2022).
bacterial infections (1 paper, 2025). "In the context of bacterial infections, such as Listeria monocytogenes (L. monocytogenes) infection, programmed cell death 6 (PDCD6) deficiency enhances antimicrobial activity by promoting LC3-associated phagocytosis, with lactate levels playing a critical role in this process." (PMID 41221394, 2025).
PDCD6 also shares sentences with these, for which no sentence is quoted: non-small cell lung carcinoma (3 papers); breast invasive carcinoma (1); chronic lymphocytic leukemia (1); colon adenocarcinoma (1); colorectal tumors (1); diffuse large B-cell lymphoma (1); esophageal carcinoma (1); Ewing sarcoma (1); hematologic malignancies (1); infertile (1); Myelodysplasia (1); myelodysplastic syndrome (1); Parkinson disease (1); pulmonary hypertension (1); rectal adenocarcinoma (1); spinal cord injury (1).